RN7SL196P (RNA, 7SL, cytoplasmic 196, pseudogene)
Gene: Miscellaneous RNA gene on chromosome 15 (30,405,307 to 30,405,597, reverse strand). Ensembl gene ENSG00000274424.
Homologues: Orthologues: pig Metazoa_SRP (52% identical). Paralogues in human: RN7SL286P (100% identical), RN7SL539P (100% identical), RN7SL796P (99% identical), Metazoa_SRP (88% identical), RN7SL106P (88% identical), RN7SL238P (88% identical), RN7SL545P (88% identical), RN7SL759P (88% identical), RN7SL536P (88% identical), RN7SL185P (80% identical), RN7SL628P (80% identical), RN7SL82P (80% identical), and 701 more.